CXCR3 (C-X-C motif chemokine receptor 3)
Diseases named in the same sentence as CXCR3 in open-access papers (continued):
Sharing a sentence is not in itself a finding about the gene and the disease.
tumor (continued). "Although ELR− CXC chemokines belong to the antiangiogenic CXC chemokine family, ELR− CXC chemokines, including CXCR3, CXCR4, CXCR5, CXCR6, and CXCR7, are associated with tumor growth, proliferation, and metastasis in PC." (PMID 33195424, 2020). "We are now using CXCR3KO mice engrafted with CXCR3+ tumor cells to dissect the direct effect of CXCL10-Ig based therapy on tumor growth." (PMID 32547545, 2020). "CD8+ T cell infiltration in advanced-stage tumor was systematically inhibited by Th17 cells via IL-17A/STAT3/CXCR3 axis." (PMID 32503584, 2020). "The natural killer (NK) cells that infiltrated into the tumor lesions expressed higher levels of CXC chemokine receptor 3 (CXCR3), as these cells expressed lower levels of interferon-γ (IFNγ)." (PMID 32457755, 2020). "Our results showed that the accumulation of CD8+ T cells in advanced-stage tumor was systematically inhibited by Th17 cells via IL-17A/STAT3/CXCR3 axis." (PMID 32503584, 2020). "A2BR antagonist, ATL801, reduces metastases by more than 80% in mice, which is due to increased IFN-γ, IFN-inducible chemokine CXCL10, a ligand for CXCR3, and tumor-infiltrating CXCR3+ T cells." (PMID 32351498, 2020). "In this case, CXCR3+ tumor-specific T cells accumulate into tumors through interaction with CXCR3 ligands (CXCL9, CXCL10, and CXCL11)." (PMID 32292786, 2020). "In this study, we show that IL-27 directly induces CXCR3 expression in conventional T cells including tumor antigen specific CD8+ T cells." (PMID 32292786, 2020). "The nuclear and cytoplasmic CXCR3 and CXCR7 correlated better with invasion, whereas the nuclear and cytoplasmic CXCR4 were both independently associated to tumour stage and survival." (PMID 32512633, 2020). "We found that PTPN2‐deficient HER‐2 CAR T cells expressed higher cell surface levels of CXCR3 in vitro prior to adoptive transfer as well as in vivo after CAR T cells had infiltrated tumours (Fig EV3C)." (PMID 31803974, 2020). "In TCGA dataset, the expression of CXCR3/5/6 in ccRCC was positively correlated with the grade of malignancy or tumor stage, and the expression levels of CXCR1/2 were negatively associated with pathological grade." (PMID 33324682, 2020). "CXCR3 is another tumor-related gene in humans with three different splice variants: CXCR3A, CXCR3B, and CXCR3-alt." (PMID 32793288, 2020). "CXCL9, CXCL10 and CXCL11, chemokine ligands for CXCR3, were expressed at high levels in the tumour locale." (PMID 32439888, 2020). "Immune cells show anti‐tumour effect against cancer cells through paracrine CXCL9, CXCL11/CXCR3 axis in tumour models." (PMID 32820615, 2020). "Alternate chemokine signalling circuits centred on CXCR3 and BLT1 have been implicated in CTL tumour trafficking and infiltration." (PMID 33046212, 2020). "CXCR3 was expressed in the tumor cells in 8/13 ALK− ALCL cases (61%), 6/11 ALK+ ALCL cases (55%) and 5/11 cHL cases (45%)." (PMID 31581676, 2019). "The CXCR3 expression was positively correlated with tumor thickness and the presence of distant metastases." (PMID 31737787, 2019). "This suggested a role for CXCR3 signaling in reinforcing the behavior of a particular tumor cell phenotype." (PMID 31831069, 2019). "This anti-tumor function of CXCR3 and its cognate ligands were attributed to the recruitment of CD8+ CTLs into tumors." (PMID 31775909, 2019). "Oral administration of A. muciniphila with FMT of non-responder feces restored the antitumor effect of anti-PD-1 mAb through the accumulation of CCR9+ CXCR3+ CD4+ T lymphocytes in mouse tumor beds." (PMID 31718585, 2019). "CXCR3 is involved in many functions, including chemotactic migration, cell adhesion, proliferation and invasion, tumor mediating immunity, angiogenesis, and metastatic spread." (PMID 31696204, 2019). "There were also more ITGAE (CD103)-expressing and CXCR3-expressing ST2+ Tregs in CRC than in adjacent tumor-free colon." (PMID 31165767, 2019).
tumor (continued). "In conclusion, we demonstrated that CXCR3 was overexpressed in GC patients and inversely associated with poor tumor differentiation, TNM stage, and depth of tumor invasion." (PMID 31240220, 2019). "We also mention CXCR2 and CXCR3 as important mediators or tumor angiogenesis, given their distinct roles with angiogenic and angiostatic chemokines, respectively." (PMID 30800123, 2019). "In the present study, we found that CXCR3 protein was primarily located in the cytoplasm of tumor cells in GC tissues." (PMID 31240220, 2019). "In contrast, the higher prevalence of CXCR3+ regulatory T cells (Tregs) in human ovarian carcinomas was suggested to dampen the effector cell response, thus favoring the progression of the tumor." (PMID 31216755, 2019). "In models of melanoma, temozolomide improved TIL recruitment into the tumor in a CXCR3-dependent manner." (PMID 31379850, 2019). "TSCC cell show an increased CXCL9 and CXCR3 expression, which results in cytoskeleton alterations and decreased cell adhesion molecules that promotes tumor cell invasion and migration to the lymph nodes." (PMID 31216755, 2019). "In a similar manner, chemokines participate in the control of metastasis of CXCR3-expressing tumor cells." (PMID 31216755, 2019). "Tumor cell frequency was reduced by 60% after the transfer of IL-15-activated Cxcr3+/+ NK cells while it was reduced by more than 85% after the transfer of the Cxcr3−/− counterpart when compared to PBS-injected mice." (PMID 31699153, 2019). "While CXCR3 and its endogenous ligands are mainly involved in inflammation and wound healing, they have also been described to have a dual role in tumor progression and immunity." (PMID 31216755, 2019). "Chemokine signaling through CXCR3 has been shown to inhibit tumor growth in several transplantable tumor models." (PMID 31775909, 2019). "In mouse models of transplanted tumors, CXCR3 signaling promotes CD8+ T cell infiltration that controls tumor growth." (PMID 31775909, 2019). "Loss of IL-17 signaling also increased the expression of CXCR3, the cognate receptor for CXCL9/10/11 chemokines, likely reflecting an increased recruitment of CXCR3-expressing lymphocytes to the tumor." (PMID 31775909, 2019). "The lack of both T-bet and EOMES results in a lower expression of CXCR3 in T cells and a drastic decrease in the number of tumor-infiltrating T cells." (PMID 31307539, 2019). "Anti-CXCR3 mAb treatment in combination with IL-15-activated NK cells and recombinant IL-15 markedly reduced tumor cell burden in the BM while the combination with control IgG had no protective effect." (PMID 31699153, 2019). "Upon transfer of IL-15 activated Cxcr3−/− NK cells, 5T33-bearing mice showed more than 50% reduction of tumor cell frequency in BM compared with mice treated with Cxcr3+/+ IL-15 activated cells or vehicle." (PMID 31699153, 2019). "CXCL9 and 10 are expressed by tumor cells and tumor-infiltrating myeloid cells, and their receptor CXCR3 is restricted to T lymphocytes." (PMID 31775909, 2019). "Our data indicate that CXCR3 blockade induces a powerful long-lasting anti-tumor effect due to the potentiation of their accumulation in BM." (PMID 31699153, 2019). "CXCR3 is a seven-transmembrane G-protein–coupled receptor which mediates tumor migration, invasion, angiogenesis, and immunity." (PMID 31696204, 2019). "More importantly, higher BM infiltration by Cxcr3−/− NK cells inversely correlated with tumor burden." (PMID 31699153, 2019). "This TIL-dependent anti-tumoral activity was furthermore validated in B16F10 tumor-bearing Rag2−/− mice, which showed a significantly increased tumor growth when transferred with CXCR3−/− cytotoxic T-lymphocytes (CTLs) compared to WT CTLs." (PMID 31216755, 2019). "In the tumor organ, CXCR3 and its ligands are expressed on the tumor cells, stromal cells, vessels and recruited leukocytes, with most all of these cells also producing various ligands." (PMID 31831069, 2019).
tumor (continued). "In this context, CXCR3-dependent NK cell infiltration was shown to be important for the lysis of tumor cells." (PMID 31704965, 2019). "Expression of CXCR3 protein was significantly increased in tumor tissues compared with corresponding paracancerous tissues (P < 0.001)." (PMID 31240220, 2019). "Since CXCR3 is important in summoning tumor-attacking T cells in tumor-surrounding areas, a reduction in CXCR3 expression in T cells indicates weakened anti-tumor immunity." (PMID 29419731, 2018). "In mouse studies with B16F10 cells, reduction of CXCR3 expression within tumor cells by anti-sense RNA resulted in less frequent metastasis." (PMID 30320116, 2018). "Conversely, specific downregulation of CXCR3 in subcutaneous injected B16F10 tumor cells reduced their metastatic capabilities to invade the tumor draining lymph node." (PMID 30420855, 2018). "Some studies suggested that IFN-γ induced ELR-negative CXC chemokine expression, which can activate downstream MAPKs, PI3K-Akt and STAT by binding to their receptor CXCR3, and thereby promote tumor progression and metastasis." (PMID 29690901, 2018). "Apart from mediating recruitment of protective immune cells, CXCL10 has been shown to reduce tumor progression independently of CXCR3." (PMID 29671006, 2018). "CXCR3 positive tumor cells are also found in invaded lymph nodes and together with other metastatic locations including the kidney, ovary and pleura." (PMID 30420855, 2018). "CXCL12-induced migration is enhanced in CXCR4+/CXCR3+/CD8+ T lymphocytes and in CXCR4+/CXCR3− malignant B cells, indicating that chemotactic cues in the perivascular environment serve as regulators for the recruitment of tumor infiltrating lymphocytes (TILs)." (PMID 30319638, 2018). "Further, the expression of CXCR3 and its ligands has been correlated with both the presence of effector T cells within tumor tissue and disease-free survival of patients." (PMID 29707158, 2018). "Proof-of-concept in a mouse model showed that the Sitagliptin-mediated DPP4 inhibition enhanced the tumor rejection by preserving the agonist form of CXCL10 and increasing the trafficking into the tumor by the CXCR3 expressing lymphocytes." (PMID 30026741, 2018). "The CXCR3 angiostatic activity is complemented with its ability to potentiate the anti-tumor immunity in several tumor systems." (PMID 29416784, 2018). "Further, a recent discovery shows that CXCR3 expression on Tregs plays a critical role in limiting the endogenous anti-tumor response as well as limiting the clinical efficacy of therapeutic anti-tumor response." (PMID 29707158, 2018). "CXCR3 expression plays an important role in recruiting NK cells to the tumor site: We showed that CXCR3 expression on human NK cells increased during ex vivo culture." (PMID 30319622, 2018). "Some studies also indicated that IL-1β induces upregulation of CXC chemokine receptor 3 (CXCR3) in different types of cells, such as T lymphocytes, natural killer cells, and tumor cells." (PMID 30359318, 2018). "The contribution of CXCR3 to tumor development in this mouse model would be consistent with a known role for inflammation in promoting DMBA/TPA tumors." (PMID 30320116, 2018). "For example, CD123+ pDCs were found to selectively express CCR2, CMKLR1, and CXCR3, receptors known to be involved in DC maturation, trafficking and recruitment at tumor sites whereas XCR1 and CX3CR1, were selectively expressed by CD141+ mDCs and CD1c+ mDCs." (PMID 29795118, 2018). "Metastasis can be promoted by endothelial cell secretion of CXCL9 (and CXCL10), assisted by VEGF, within the tumor microenvironment or autocrine CXCL10/CXCR3 interactions on tumor cells." (PMID 30320116, 2018). "It is well known that CXCR3 facilitates Th1 and Teffs recruitment to the site of inflammation and facilitates Tregs recruitment to the same site, thus limiting the effectiveness of CXCR3+Teffs function in anti-tumor immunity." (PMID 29707158, 2018).
tumor (continued). "This review describes the differential role of CXCR3 induction on peripheral and tumor microenvironment inflammation." (PMID 29707158, 2018). "Higher percentages of Granzyme B and CXCR3 were identified on ADAM28 KO CD8+ T cells isolated from tumor-bearing lungs, which can be correlated to the increased tumor density in ADAM28 KO lungs used for this assay." (PMID 30647853, 2018). "In this regard, the design of small molecule antagonists of CXCR3 should be beneficial, particularly if precisely targeted to the tumor cells." (PMID 30320116, 2018). "The CXCL9/10/11-CXCR3 signaling pathway in tumor microenvironment mainly facilitated the chemotactic movement of CXCR3 activated immune cells to the tumor site for anti-tumor immunity." (PMID 29690901, 2018). "Gene profiling of BCC and SCC tumor tissue suggests an increase in IFN related genes including CXCL9 while immunohistochemical staining demonstrated the presence of CXCR3+ immune cells." (PMID 30320116, 2018). "In the early stages of MF, expression of CXCL9, CXCL10, and CXCR3 is believed to be important for recruitment and accumulation of tumor cells in the skin." (PMID 29915722, 2018). "Several studies have also shown that CXCR3 expression on T cells, or expression of CXCL9 and CXCL10 in tumor tissue, is associated with increased TIL accumulation and a favourable clinical outcome in CRC." (PMID 29671006, 2018). "This has consequences for anti-tumor therapy when CXCR3 blocking agents are used considering that CXCR3-A has a pro-tumor properties and CXCR3-B exhibits anti-tumor activity." (PMID 28878333, 2017). "In all of these cases, the monoclonal MAB160 anti-CXCR3 antibody significantly inhibited ascites-directed tumor cell migration." (PMID 28504691, 2017). "This is likely mediated through a CXCR3-dependent chemoattraction of tumor cells to the enhanced secretion of the chemokine ligands, CXCL9 and 10, by peritoneal membrane fibroblasts (PMF)." (PMID 29050279, 2017). "Previous studies have shown that IP10 chemoattracts CXCR3-positive lymphocytes to tumor areas, and promotes activation of CD4+ Th and CD8+ Tc lymphocytes." (PMID 28915590, 2017). "Most importantly, CXCR3 is localized at the tumor cell membrane in invasive areas, while in angiogenic parts of the tumor CXCR3 is mostly found at an intracellular location." (PMID 29146996, 2017). "Our lab is pursuing targeted intervention strategies to dysregulate myeloid cell CXCR3 activity in order to reduce metastatic engraftment and tumor progression in the lungs." (PMID 28358049, 2017). "While our study demonstrates the requirement of CXCR3-expressing monocytes for efficient tumor engraftment, the cellular mechanism remains undefined." (PMID 28358049, 2017). "In the discovery set, tumor cell CXCR3 was scored 0 (2/60, 3%), 1+ (13/60, 22%), 2+ (28/60, 47%) and 3+ (17/60, 28%)." (PMID 28504691, 2017). "We focused on CXCR3-A conformation and on the mechanisms controlling its activity and trafficking and investigated the role of CXCR3/LRP1 cross talk in tumor cell invasion." (PMID 29146996, 2017). "Contrarily, other B-cell subsets like CXCR3+ B cells that constitute approximately 45% of tumor-infiltrating B cells were shown to positively correlate with early recurrence of HCC and induce a protumorigenic activity of tumor-associated macrophages." (PMID 29050338, 2017). "They concluded that presence of DPP4 would repress CXCR3-mediated anti-tumor immunity and thus limited the infiltration of T lymphocytes." (PMID 27936466, 2017). "As a member of the CXC chemokine family, CXCL10 binds to its receptor CXCR3 to exert biological functions in infectious diseases, immune dysfunction, chronic inflammation, tumor development and metastasis." (PMID 27765529, 2017). "Combining the two cohorts, the prognostic effect of high tumor cell CXCR3 on OS was stronger in optimally debulked patients than in those with residual tumor after primary cytoreductive surgery." (PMID 28504691, 2017).
tumor (continued). "These chemokines are well known for their anti-tumor roles in recruiting and activating a wide array of immune cells mediated through a common receptor Cxcr3,41 also upregulated by the combination." (PMID 28920002, 2017). "Bearing in mind that chemokine receptors primarily facilitate cell migration, one plausible explanation is that CXCR3 mediates tumor cell migration out of the primary tumor." (PMID 28504691, 2017). "LRP1 was localized in tumor, stroma, and vascular cells, whereas CXCR3 was only detected in tumor cells and localized in the cytoplasm." (PMID 29146996, 2017). "Collectively, these data establish a correlation between tumor engraftment and monocyte/macrophage accumulation in lung, implicating CXCR3+ monocytes/macrophages as cellular mediators of engraftment." (PMID 28358049, 2017). "In support of this, CXCR3 mediated the migration of tumor cell lines OVCAR3 and SKOV3 toward malignant ascites, which was inhibited by a monoclonal anti-CXCR3 antibody in vitro." (PMID 28504691, 2017). "This is supported by our finding that CXCR3 overexpression discriminated best between poor and good outcome in patients after complete tumor resection." (PMID 28504691, 2017). "Tumor engraftment to lung was impaired in CXCR3−/− mice, and transient reconstitution with circulating CXCR3-replete monocytes was sufficient to restore engraftment." (PMID 28358049, 2017). "PB CD56highCD16± NK cells express CD62L, CCR7, CXCR4, and CXCR3 that allow their preferential recruitment to secondary lymphoid organs, tumor, and inflamed tissues." (PMID 28360915, 2017). "We present a new foundational role for CXCR3+ monocytes/macrophages in the process of tumor engraftment in the lung." (PMID 28358049, 2017). "This is supported by our detection of CXCR3 ligands in mesothelial cells and malignant ascites and the reduced tumor cell migration toward this peritoneal milieu upon CXCR3 inhibition." (PMID 28504691, 2017). "Further analysis of the clinicopathologiacal characteristics in 89 paired HCC tissues showed CXCR3 expression was positively correlated with the tumor side(p=0.014), tumor differentiation(p=0.014), portal invasion(p=0.028), and metastasis(p=0.017)." (PMID 26883105, 2016). "In HCC tissues, CXCR3 was frequently upregulated and correlated with tumor size, tumor differentiation, portal invasion and metastasis." (PMID 26883105, 2016). "In mice, using NK cell-sensitive tumor models, it has been shown that IFN-γ can induce the release of CXCL9-10 by tumor-infiltrating immune cells leading to the recruitment of CXCR3+ NK cells." (PMID 27294158, 2016). "Emerging evidence suggests that the CXCR3 signalling network can positively influence tumour cell growth and metastasis." (PMID 27297979, 2016). "This has been related to the IFN-γ promotion of CXCL9 and CXCL10 production by tumor-infiltrating leukocytes, leading to the CXCR3-mediated recruitment of mouse CD27high NK cells, the population of NK cells with the higher functional potential." (PMID 27766097, 2016). "Activated CD8+ T cells up-regulate expression of chemokine receptors such as CXCR3 and they are attracted to tumor sites expressing CXCR3 ligands such as CXCL9, CXCL10 and CXCL11." (PMID 27619885, 2016). "Chemokines CXCL9, 10, and 11 signal via their common receptor CXCR3 and thereby recruit lymphocytes to inflammation sites and enable their penetration into the tumor tissues." (PMID 28123870, 2016). "Meanwhile, in breast cancer, CXCL10/CXCR3 axis presented with tumor infiltrating lymphocytes (TILs), tumor progression and invasion, and poor prognosis." (PMID 26910919, 2016). "We report that genetic targeting of CXCR3 in both tumor cells and host-derived cells showed tumor-inhibitory effect." (PMID 26485767, 2015). "Together, these data suggest that CXCR3-mediated signals likely promote tumor cell migration and mobility, and contribute to metastasis." (PMID 26485767, 2015).